RNY3 (RNA, Ro60-associated Y3)
Synonyms: hY3; Y3
Gene: Miscellaneous RNA gene on chromosome 7 (148,983,755 to 148,983,856, forward strand). Ensembl gene ENSG00000202354.
Homologues: Orthologues: chimpanzee Y_RNA (100% identical), guinea pig Y_RNA (100% identical), macaque Y_RNA (99% identical), rabbit RNY3 (98% identical), mouse Rny3 (95% identical), rat Y_RNA (95% identical). Paralogues in human: Y_RNA (97% identical), RNY3P1 (96% identical), Y_RNA (96% identical), Y_RNA (95% identical), Y_RNA (94% identical), Y_RNA (93% identical), Y_RNA (92% identical), Y_RNA (91% identical), RNY3P11 (90% identical), RNY3P14 (90% identical), Y_RNA (90% identical), RNY3P16 (89% identical), and 99 more.
Diseases named in the same sentence as RNY3 in open-access papers:
RNY3 is named in the same sentence as 25 diseases in open-access papers, as found by Europe PMC text mining. Sharing a sentence is not in itself a finding about the gene and the disease. The quoted sentences say what the papers report.
bladder cancer (3 papers, 2017 to 2024). "siRNA mediated knock-down of RNY1 and RNY3 reduced the number proportion of S phase cells in the HeLa cells; degradation of RNY3 reduced also the number S-phase cells in EJ30 bladder cancer cells." (PMID 29126388, 2017). "These Y RNAs (RNY1, RNY3, RNY4, and RNY5) are reportedly similarly downregulated in human bladder cancer versus normal urothelial bladder tissue and act as a prognostic indicator for this condition." (PMID 37835660, 2023). "Overall, the downregulated hypoxia-related Y RNA expression trend in COM is consistent with the expression level of Y RNAs (RNY1, RNY3, RNY4, RNY5) in human melanoma, prostate, and urinary bladder cancer, and appears to distinguish the metastatic and non-metastatic melanoma." (PMID 38288969, 2024).
benign prostate hyperplasia (1 paper, 2023). "Oncologists focusing on the human prostate have found that RNY1, RNY3, RNY4, and RNY5 are downregulated in prostate adenocarcinoma versus normal tissue and benign prostate hyperplasia." (PMID 37835660, 2023).
lymph node metastasis (1 paper, 2017). "Presence of lymph node metastases was also associated with decreased RNY1 (p < 0.001), RNY3 (p < 0.001) and RNY4 (p = 0.007) expression." (PMID 29126388, 2017). "RNY1, RNY3 and RNY4 expression was associated with advanced stage (muscle invasive BCA, lymph node metastasis) and grade (G3 tumors when opposed to G1 and G2)." (PMID 29126388, 2017). "A low expression of RNY1, RNY3 and RNY4 was associated with muscle-invasive BCA, lymph node metastases and advanced grade." (PMID 29126388, 2017).
urothelial carcinoma (1 paper, 2017). A malignant neoplasm derived from the transitional epithelium of the urinary tract (urinary bladder, ureter, urethra, or renal pelvis). "The expression of all four YRNAs (RNY1, RNY3, RNY4, RNY5) was determined in archival BCA (urothelial carcinoma, n = 88) and normal urothelial bladder (n = 30) tissues using quantitative real-time PCR." (PMID 29126388, 2017).
cancer (5 papers, 2008 to 2024). A tumor composed of atypical neoplastic, often pleomorphic cells that invade other tissues. "We also performed univariate and multivariate Cox regression analyses: RNY1 and RNY3 were significantly predictive for cancer-specific and overall survival (all p < 0.05), but lost their predictive value in a multivariate model." (PMID 29126388, 2017). "Importantly, the expression levels of RNY1 and RNY3 were significantly predictive for cancer-specific and overall survival of BCA patients with a clear trend for RNY4." (PMID 29126388, 2017). "C. ATAC-seq values for of human vtRNA3-1P, vtRNA2-2P and RNYs (RNY1, RNY3, RNY4 and RNY5) in 21 different tumors with at least 5 tumor samples available in Pan-Cancer TCGA dataset (385 tumors samples) expressed as log2 normalized values." (PMID 34354812, 2021). "The distribution of ATAC-seq values for of human vtRNA3-1P, vtRNA2-2P and RNYs (RNY1, RNY3, RNY4 and RNY5) in Pan-Cancer TCGA dataset (385 tumors samples across 23 cancer types) expressed as log2 normalized values." (PMID 34354812, 2021). "YRNAs are overexpressed in various cancer cells, and RNY1 and RNY3 inhibition was shown to decrease cell proliferation." (PMID 29126388, 2017). "Expression of YRNA was significantly correlated with BCA patients’ overall (RNY1, RNY3, RNY4) and cancer-specific (RNY1, RNY3) survival (all log rank p < 0.05)." (PMID 29126388, 2017). "Furthermore, expression of RNY1 and RNY3 was predictive for BCA patients’ overall (also RNY4) and cancer-specific survival as estimated using Kaplan-Meier and univariate (but not multivariate) Cox regression analyses." (PMID 29126388, 2017).
tumor (3 papers, 2014 to 2018). "RNY1, RNY3 and RNY4 show good discriminative ability between tumor and normal tissue, as well as between muscle-invasive and non-muscle-invasive urothelial carcinoma." (PMID 29126388, 2017). "In our study we were able for the first time to show that RNY1, RNY3 and RNY4 could very good discriminate between the normal and tumor tissue with a maximal AUC of 0.863 (RNY3), and to a lesser extent between muscle-invasive and not-muscle-invasive tumors (maximal AUC 0.780 for RNY3)." (PMID 29126388, 2017).
RNY3 also shares sentences with these, for which no sentence is quoted: clear cell renal cell carcinoma (2 papers); colon cancer (2); Hydrocephalus (2); adenocarcinoma (1); allergic disease (1); asthma (1); cervical cancer (1); communicating hydrocephalus (1); COVID-19 (1); infection (1); inflammation (1); kidney cancer (1); kidney tumours (1); melanoma (1); pancreas cancer (1); pancreatic ductal adenocarcinoma (1); prostate adenocarcinoma (1); prostate tumours (1); viral infection (1).